RN7SL752P (RNA, 7SL, cytoplasmic 752, pseudogene)
Gene: Miscellaneous RNA gene on chromosome 3 (129,591,349 to 129,591,635, forward strand). Ensembl gene ENSG00000239437.
Homologues: Orthologues: chimpanzee Metazoa_SRP (93% identical), macaque Metazoa_SRP (80% identical), pig Metazoa_SRP (74% identical). Paralogues in human: RN7SL5P (78% identical), RN7SL1 (78% identical), RN7SL2 (77% identical), RN7SL3 (77% identical), RN7SL4P (75% identical), RN7SL126P (74% identical), RN7SL278P (72% identical), RN7SL357P (72% identical), RN7SL18P (72% identical), RN7SL33P (72% identical), RN7SL45P (72% identical), RN7SL665P (72% identical), and 703 more.